TNF (tumor necrosis factor)
Diseases named in the same sentence as TNF in open-access papers (continued):
Sharing a sentence is not in itself a finding about the gene and the disease.
COVID-19 (continued). "On the contrary, we saw a difference in terms of TNF-α levels (higher in HIV/COVID-19 than in HIV group) and IL-1β (higher in the HIV group than in the group of coinfected participants)." (PMID 35891555, 2022). "Vitamin D has also been proven to diminish TNF-α levels, implying another treatment approach for combating the COVID-19 cytokine storm." (PMID 36558489, 2022). "Recently, one study demonstrated that the TNF/IL1B–driven inflammatory response was dominant in COVID-19 across all types of cells among PBMCs using single-cell RNA sequencing." (PMID 36159873, 2022). "Overall, studies suggest that type I IFN responses are dysfunctional in severe COVID-19 and correlate with TNF- and IL-1β-driven inflammation in patients with severe disease." (PMID 35244141, 2022). "As TNF-α concentration rises in the first stages of COVID-19, it is suggested as a remarkable trigger for inflammatory cascade, leading to cytokine storm that in turn results in fatal pneumonia and acute respiratory distress syndrome (ARDS)." (PMID 36574379, 2022). "This showed that being on anti-TNFα therapy for underlying rheumatic disease, psoriasis or IBD, was significantly associated with a lower likelihood of COVID-19-related hospitalization." (PMID 36579506, 2022). "This randomised controlled trial includes a targeted approach for the use of an anti-inflammatory therapy with the TNF-α-antibody infliximab in a selected group of patients with COVID-19 and clearly defined hyperinflammation." (PMID 36056419, 2022). "In the cytokine storm that takes place in COVID-19, elevated levels of cytokines such as TNF-α and IL-8, induce further ROS production." (PMID 36294388, 2022). "After stimulating myeloid blood cells with R848, we observed that multiple myeloid subsets from COVID-19 patients had lower levels of IFNβ and higher levels of TNF, IL-6, IL-12, CCL3, and CCL4 than cells from healthy controls." (PMID 36085197, 2022). "In this study, we identified that the serum levels of IL-6, IL-2R, IL-10, TNF-α, IL-1β, IL-4, IL-8 and IL-17 were significantly elevated in the severe or death cases and probably play crucial roles in the progression of COVID-19." (PMID 35237162, 2022). "The network pharmacology showed CHM formulas affected several inflammation-related proteins for COVID-19, including IL-10, TNF-α, IL-6, TLR3, and IL-8, in which Dexamethasone and Aspirin covered only IL-10 and TNF-α." (PMID 35890093, 2022). "IL-6 and TNF-α levels were statistically different in the four age groups between COVID-19 patients and healthy controls; P=0.036 and P=<0.001, respectively." (PMID 36381078, 2022). "The results of the present study showed that in the plasma of COVID-19 patients, the expression of pro-inflammatory cytokines—TNFα and IL-6 and the anti-inflammatory interleukin—IL-10 increases, especially in the plasma of recovered COVID-19 patients." (PMID 36233111, 2022). "Pro-inflammatory cytokines IL-6, TNF-α, IL-8, IL-1α, anti-inflammatory cytokine IL-4, and the IP-10 chemokine were induced in the severe presentation of COVID-19 during pregnancy." (PMID 36016660, 2022). "One study showed that levels of TNF-α, IL-6 and IL-8 were significantly lower in COVID-19 patients than in patients with bacterial sepsis with or without ARDS." (PMID 36289881, 2022). "In post-COVID-19 patients, some plasma cytokines (i.e. TNF-α, IL-18, CXCL8, CXCL10, CCL2, CCL3, and CCL4) remained higher than in HCs, but levels were much lower as compared to hospitalised patients." (PMID 36275702, 2022). "As an example, pDCs from COVID-19 patients seem to have increased TNF signaling, while the same pathway is decreased in monocytes." (PMID 35244141, 2022). "The possible COVID-19 pain pathway pathomechanism engaging interleukin (IL)-1, IL-6, and tumor necrosis factor (TNF) alpha aided with a cortical spreading depression disturbing the hypothalamus is also described in this study." (PMID 36284805, 2022).
COVID-19 (continued). "Our previous studies in 3D tissue models have shown that cannabis extracts downregulate the expression of ACE2, IL-6, and TNF-α, the key factors in COVID-19 progression." (PMID 35277472, 2022). "Even modest COVID-19 can induce proinflammatory effects, seen by elevated IL-1b, IL-6, TNFα, MCP-1 & IP-10, leading to insulin resistance." (PMID 35165505, 2022). "IFN-γ and TNF-α levels were higher in symptomatic HCWs than patients with COVID-19 and those who died." (PMID 35336861, 2022). "Supporting this, patients with severe COVID-19 had markedly higher levels of IL-6 and TNFα pro-inflammatory cytokines compared to patients with mild-to-moderate disease." (PMID 35468973, 2022). "Elegant evidence from the COVID-19 pandemic shows that IL-6 and TNF-α are involved in the COVID-19-induced cytokine storm." (PMID 35784318, 2022). "We found that CD4+ cells from severe convalescent patients had significantly higher capacity to produce TNF-α, IL-2 and CD107a at time-point I, compared to healthy controls and mild/moderate COVID-19 convalescents." (PMID 35757700, 2022). "Several studies have found significantly high levels of inflammatory cytokines such as TNF-α and IL-6 in COVID-19 patients." (PMID 36092161, 2022). "SARS-CoV-2 appears to downregulate the expression of ACE-2 on peripheral blood monocytes which show an activated phenotype in COVID-19 evidenced by morphology and IL-6, IL-10, and TNF-α production." (PMID 35913134, 2022). "Previous studies have reported increased concentrations of IL-6,10 and TNF-α in severe cases of COVID-19." (PMID 36138753, 2022). "As early as 2020, a new edition of anti-tumor necrosis factor therapy (TNF-α) for COVID-19 has been proposed by scholars." (PMID 36494757, 2022). "Drug subanalysis showed that TNF inhibitors (TNFi) were more frequently used in COVID-19– patients (41.9 vs.14.8% in COVID-19+, P < 0.001)." (PMID 35770002, 2022). "Our cohort included 52 patients who received anti-TNF treatments and experienced only a mild course of COVID-19." (PMID 35335008, 2022). "High levels of proinflammatory cytokines, such as IL-1, IL-6, IL-7, IL-12, IFN-γ, TNF-α, IP-10, MIP-1A, MCP-1, GCSF, and IP-10, have been observed in COVID-19 patients and are generally associated with severe lung damage." (PMID 34463916, 2022). "Some studies have pointed out that TNF-α can combine with other cytokines to play a role in tissue damage and excessive inflammation during COVID-19." (PMID 36146616, 2022). "In conclusion, the major cytokines in COVID-19 pathophysiology, including IL-6, IL-8, and TNF-α, are significantly improved by Photobiomodulation, as is the IL-6/IL-10 ratio." (PMID 35874678, 2022). "Clinical evidence also points to the increased levels of tumor necrosis factor-alpha (TNF-α) in COVID-19 patients which is accompanied by the raised levels of other cytokines that lead to aggravated immune response." (PMID 36081516, 2022). "For the MGH cohort, comparable tertile groups were created according to TNF-α, IL-1β, IL-6 and IL-8 at admission for both mild and severe COVID-19." (PMID 35938070, 2022). "In fact, increased gene expression of inflammatory responses and TNF-α signaling via NF-κB were reported after COVID-19 vaccination." (PMID 35943812, 2022). "Similar to what is seen in COVID-19 patients’ lung autopsy tissues, their results revealed that robust induction of chemokines (such as rheumatoid arthritis, TNF signaling, and IL-17 signaling) upon SARS-CoV-2 infection." (PMID 36578545, 2022). "Our results reported that mothers affected by COVID-19 have an increase in pro-inflammatory factors (TNF-α, IL-2, TGF-β, IL-6 and IL-8) and at the same time, in anti-inflammatory agents such as IL-10, when compared to controls." (PMID 35408809, 2022). "The evidence also indicated that the severity of COVID-19 increases with the levels of inflammatory mediators including cytokines and chemokines such as IL-2, IL-7, IL-10, and TNF-α in the blood due to COVID-19 infection." (PMID 36091037, 2022).
COVID-19 (continued). "The most important inflammatory mediators released by immune cells during the “cytokine storm” are IFN-α, IFN-γ, IL-1β, IL-6, IL-12, IL-18, IL-33, TNF-a, and TGF-β and they are associated with different clinical features of COVID-19." (PMID 36298472, 2022). "In this study, out of 1238 variant previously reported to be association with susceptibility and severity of COVID-19, we confirmed 49 variants, corresponding to 18 independent loci, including 3p21.31 locus, ABO, IFNAR2, TNF, APOE, and FOXP4-AS1 gene." (PMID 36531218, 2022). "We have reported the application of a cytokine panel (serum, IL-1β, IL-6, IL-8 and TNFα) using the automated EllaTM platform and its potential clinical utility in the assessment of patients with COVID-19." (PMID 35500008, 2022). "The levels of intracellular TNFα and interleukin 1 receptor type 2 (cIL1R2) in leukocytes were higher in HCs than in COVID-19 patients during their first ICU week (p < 0.001)." (PMID 35625671, 2022). "Characterization of serum cytokines present in patients with COVID-19 demonstrates elevated levels of TNF and IL-6, and IL-1Ra completely abrogates IL-6 and TNF release from SARS-CoV-2-infected primary human monocytes." (PMID 38566906, 2022). "The pathogenesis of COVID-19 encompasses a “cytokine storm” which includes pro-inflammatory interleukins (IL-1β, IL-6) and the tumor necrosis factor (TNF-α)." (PMID 35925914, 2022). "Given the profound role of excessive TNF in the development, pathogenesis, and poor outcome of COVID-19, blockade of TNF offers a clinically effective intervention in this regard." (PMID 35619180, 2022). "The pathological feature of COVID-19 is that active viral replication activates a variety of immune cells and produces a large number of inflammatory cytokines such as TNF, IL-6, IL-1β, IL-17 and IFN-γ, resulting in cytokine storm." (PMID 35935817, 2022). "Peripheral immune response and increased cytokine production, including an early surge in TNF and IL-1β concentrations activate glia, leading to aggravation of neuroinflammation and dysfunction of neurons during COVID-19." (PMID 36230921, 2022). "We evaluated IL-17A, TNFα, IL-1β protein levels in saliva of COVID-19 patients with different severities, and found that among these cytokines, IL-17A was associated with COVID-19 severity and poor patient survival outcomes." (PMID 36136963, 2022). "The major cytokines in COVID-19 pathophysiology, including IL-6, IL-8, and TNF-α, responded positively to PBM therapy and opened a new window for inhibiting and managing a cytokine storm within only 3-10 days." (PMID 35874678, 2022). "SSRIs decreased plasma levels of four of 16 tested inflammatory mediators, including interleukin (IL)-10, tumor necrosis factor (TNF)-α, and CCL-2, which are associated with COVID-19 severity, and IL-6, which highly plays a role in disease mortality." (PMID 36532776, 2022). "A significant increase in 40 analytes was identified, including IL-1, IL-2, IL-6, IL-10, IFN-γ, and TNF-α, which are important proinflammatory cytokines that have been established in patients with COVID-19." (PMID 36290634, 2022). "Our findings also align with the results of a study conducted on 41 COVID-19 confirmed cases in China, which found that IL-6, IL-7, TNF, and IL-10 were upregulated in the plasma of the study subjects." (PMID 36239108, 2022). "Studies report either robust activation of the T-cells in critical cases with a high percentage of IFN-γ-producing CTL cells or severe COVID-19 as an immunosuppressive phenotype, exemplified by profound declines in IFNγ- and TNF-producing T cells." (PMID 35401519, 2022). "A study in California suggested that patients who went on to develop PASC had a higher level of the proinflammatory cytokines TNF-α and IP-10 during early recovery from acute COVID-19." (PMID 36070309, 2022). "In patients with severe COVID-19, the production of TNF-α and IL-6 is sustained by circulating monocytes." (PMID 36056419, 2022).
COVID-19 (continued). "In addition, purified CD8+ T lymphocytes from patients with severe COVID-19 showed increased constitutive expression of differentially expressed genes associated with the caspase pathway, inflammasome, and antiviral factors, and, curiously, had reduced expression of TNF-α." (PMID 36359755, 2022). "Incubation with the TLR7/TLR8 agonist induces the production of TNF-α and IL-6 in cells from HDs and COVID-19 patients." (PMID 36248842, 2022). "When MAIT cells were stimulated with E. coli, typical upregulation of IFNγ was observed but levels of TNFα and IL-17A were significantly lower in COVID-19-positive individuals compared to healthy controls." (PMID 34050887, 2022). "MMP-7, TGF-β, IL-10, IL-7, TNF-α, and IL-6 were correlated with high lung involvement in COVID-19 patients." (PMID 36286038, 2022). "In comparison to mild/moderate cases of COVID-19, plasma from patients with severe cases showed a greater tendency for levels of IL-6, IL-8 and TNF-α indicating a pro-inflammatory response." (PMID 35958594, 2022). "Markedly high levels of notably IL-6, IL-10 and TNF-α have been reported in patients with severe COVID-19." (PMID 35956081, 2022). "According to our study, group S presented high levels of TNF-alpha, which contributes to endothelial activation processes and vascular occlusion, suggesting that sICAM-1 is a predictor for severe cases of COVID-19." (PMID 36163447, 2022). "The significant increase in proinflammatory cytokines such as interleukin (IL)-6, IL-8, and tumor necrosis factor-alpha (TNF-a) in severely ill SARS-CoV-2 patients implies that cytokine storm formation is crucial for COVID-19 clinical progression." (PMID 35923492, 2022). "S5, S6, and S7 cells exhibited relatively aged states that highly expressed CXCL4 and ARG1 but lower SELL, which accounted for the majority of aged neutrophils, while S7 cells also showed the highest TNF-α expression in both KD and severe COVID-19 patients." (PMID 36159873, 2022). "The cytokine storm in COVID-19 is characterized by an overproduction of tumor necrosis factor-alpha (TNF), interleukin-1 (IL-1), IL-2, IL-6, and interferons." (PMID 36011823, 2022). "Serological TNF-α, IL-6, CCL4 and IL-4 levels were higher in P-COVID-19+ than in P-COVID-19-, although TNF-α was significantly higher in P-COVID-19+ than in P-COVID-19-." (PMID 35901034, 2022). "Oral tannins extracted from quebracho and chestnut in combination with B12 vitamin and standard treatment reduced macrophage inflammatory protein-1α (MIP-1α) and TNF-α levels in hospitalized COVID-19 patients." (PMID 35874955, 2022). "Unexpectedly, pro-inflammatory monocyte markers such as IL1B and TNF are downregulated in COVID-19 monocytes relative to controls, both in progressive and in stable patients, although IL1B was slightly less downregulated in stable patients." (PMID 35064122, 2022). "During COVID-19, many cytokines such as IL-6, IL-10, and TNF-α are markedly higher, whereas T lymphocytes are much lower." (PMID 36278672, 2022). "Cytokine storms begin with strong activation of cytokine-secreting cells, and COVID-19 cytokine storms are characterized by high expression of IL-6 and TNF-α." (PMID 36091053, 2022). "Numerous cytokines and chemokines are profoundly elevated in patients with severe COVID-19, including cytokine IL-6, TNFα, and chemokine IL-8." (PMID 35277472, 2022). "Despite certain medical societies’ recommendations against starting or continuing bDMARDs (including anti-TNF medications) in areas where COVID-19 has been circulating in the population, anti-IL-6 medications have been deemed to be safer." (PMID 35054471, 2022). "Therefore, in the current pilot study, we quantified the concentration of IL-26 in plasma samples from patients with acute COVID-19 (COVID-19 group), compared with healthy control subjects (Control group), and analyzed its association with the neutrophil-mobilizing cytokines IL-6, IL-8, and TNFα." (PMID 36466824, 2022).
COVID-19 (continued). "We also measured saliva levels of TNFα and IL-1β, as known markers of inflammation and organ damage, and commonly reported to be elevated in blood of patients with COVID-19." (PMID 36136963, 2022). "Many clinical trials in the context of COVID-19 treatments confirmed this point of view, such as IL-6 blockers, IL-1 receptor antagonists, TNF-α inhibitors, JAK inhibitors, and corticosteroids." (PMID 36111104, 2022). "The latest studies have shown elevated levels of inflammatory cytokines in patients with COVID-19, such as interleukins and tumor necrosis factor (TNF)-α." (PMID 35456120, 2022). "Plasma levels of IL-2, IL-7, TNF-α, and other pro-inflammatory cytokines were elevated in COVID-19 patients, and levels of various inflammatory cytokines were higher in (ICU) patients than in non-ICU patients." (PMID 36299906, 2022). "Both IFN-γ and TNF-α were significantly higher in symptomatic HCWs compared to symptomatic and deceased patients with COVID-19." (PMID 35336861, 2022). "At present, there are ongoing clinical protocols to identify the efficiency of the anti-TNF therapy in COVID-19, some of them suggesting that COVID-19 patients treated with anti-TNF agents have a better prognosis." (PMID 35631442, 2022). "The results showed that the common KEGG pathways of COVID-19, RA, AS and GA mainly includes Coronavirus disease, IL-17 signaling pathway, Th17 cell differentiation, TNF signaling pathway and Toll-like receptor signaling pathway." (PMID 35935817, 2022). "TNF-α and IL-6 production upon different stimuli were similar between healthy individuals and convalescent COVID-19 patients." (PMID 35464396, 2022). "IL1B, P2RX7, IFNB1, IFNB1, TNF, and CASP1 enhance the network connectivity between multiple sclerosis (MS) complex genomes associated with COVID-19 and NOD-like receptor (NLR) signaling." (PMID 36483456, 2022). "In most studies, compared with healthy controls, COVID-19 patients had significantly higher levels of interleukin (IL)-2, IL-4, IL-6, IL-10, tumor necrosis factor (TNF)-α, and C-reactive protein (CRP) and lower lymphocyte counts." (PMID 35310853, 2022). "Meanwhile, elevated levels of serum IL-2, TNF-α, IL-7, granulocyte colony-stimulating factor, and interferon-gamma-induced protein 10 were correlated with the severity of COVID-19." (PMID 36299906, 2022). "The TNF-α, IL-6, MIP1b and IL-4 concentrations were higher in the P-COVID-19+ than the P-COVID-19- patients." (PMID 35901034, 2022). "This framework releases large amounts of pro-inflammatory cytokines, as in COVID-19, including IL-6, TNF, IL-1β, IL-12, IL-17, IL-18, IP-10, IFN-γ, CCL2 and CCL5." (PMID 35843719, 2022). "In acute phase of COVID-19, TNF-α is widely present in blood and infected tissues and acts as an amplifier of inflammation." (PMID 35237624, 2022). "High levels of pro-inflammatory markers (IL-6, IL-8, IL-10, and TNF-α) were detected in the cerebrospinal fluid (CSF) collected from COVID-19 patients exhibiting neurological symptoms and/or meningoencephalitis." (PMID 35625737, 2022). "In the randomized double-blinded trial with 60 severe COVID-19 patients, the Xuebijing injection suppressed the cytokine storm by regulating the TNF-α, IL-6, and IL-8." (PMID 36072401, 2022). "Our data support further investigation of the use of anti-TNF agents in the early time course of patients with severe COVID-19." (PMID 36060521, 2022). "A massive pro-inflammatory profile mediated by IL-1β, IL-6, TNF and IFN-γ together with lower levels of IL-10 was a systemic hallmark of critically ill COVID-19 patients." (PMID 35720401, 2022). "Induction of CD39 expression occurs upon cellular activation and is regulated by hypoxia, oxidative stress, and inflammatory cytokines such as IL-6 and TNF-α, which are frequently increased in COVID-19 patients." (PMID 36248842, 2022).